RXRG (retinoid X receptor gamma)
Diseases named in the same sentence as RXRG in open-access papers (continued):
Sharing a sentence is not in itself a finding about the gene and the disease.
bipolar disorder (3 papers, 2010 to 2015). A disorder of the brain that causes unusual shifts in mood, energy, activity levels and the ability to carry out day-to-day tasks. "Moreover, ARNTL, RORA, RORB and RXRG were associated with bipolar disorder in a meta-analysis integrating data from genome-wide association studies and human and animal model expression studies." (PMID 20195522, 2010). "Overall, our study provides evidence for the association of CMYA5, MCTP1, RXRG, and TNR with bipolar disorder." (PMID 26190982, 2015). "We find that the calcium signaling pathway is enriched in genes commonly coexpressed with RXRG and TNR, and disruptions in calcium signaling are part of the pathophysiology of bipolar disorder." (PMID 26190982, 2015). "We then investigate the homologous genomic regions in human bipolar disorder GWAS data and thus identify four candidate genes (TNR, RXRG, MCTP1, and CMYA5)." (PMID 26190982, 2015).
dyslipidemia (3 papers, 2013 to 2021). "The present study suggests that variation in the RXRG gene may contribute to the genetic dyslipidemia in FCHL subjects, suggesting a possible genetic role in determining this trait." (PMID 24222859, 2013). "The defective activation of cholesterol efflux by the LXR/RXR heterodimer might therefore contribute to the effects of RXRG gene on dyslipidemia." (PMID 24222859, 2013). "In conclusion, variation in the RXRG gene may contribute to the genetic dyslipidemia in FCHL subjects." (PMID 24222859, 2013). "Variation in the RXRG gene may contribute to genetic dyslipidemia in FCHL subjects." (PMID 31772600, 2019).
gastric cancer (3 papers, 2022 to 2024). A primary or metastatic malignant neoplasm involving the stomach. "In this single-institution/retrospective clinical and translational study (RAR-GASTRIC), we define the expression of RARα, RARβ, RARγ, RXRα, RXRβ and RXRγ in stomach tumors with the use of archival tissue samples obtained from gastric cancer patients." (PMID 39323992, 2024). "By converse, our data indicated that gastric cancer samples tended to express low levels of the RARγ and RXRγ mRNAs." (PMID 39323992, 2024). "In this study, we determine the RNA expression of the six isoforms of Retinoic-Acid-Receptors (RARα/RARβ/RARγ/RXRα/RXRβ/RXRγ) in view of their potential use as gastric cancer progression markers and/or therapeutic targets." (PMID 39323992, 2024). "To identify the RAR isoform(s) underlying the anti-proliferative action of the retinoid, initially, we evaluated the constitutive expression of RARα, RARβ, RARγ, RXRα, RXRβ and RXRγ mRNAs in our gastric-cancer cell-lines." (PMID 37951921, 2023). "Finally, high levels of the RXRγ transcript presented a significant correlation only with the HER2-negative status of gastric cancer (p=0.017)." (PMID 39323992, 2024).
hyperlipidemia (3 papers, 2014 to 2025). "RXRγ has also been linked to the regulation of adipose differentiation-associated protein, which accelerates neutral lipid accumulation, and contributes to familial combined hyperlipidaemia." (PMID 40855678, 2025).
lung carcinoma (3 papers, 2013 to 2022). "A report on RXR has shown that RXRG methylation is increased in lung cancer, which downregulates RXRG, and this methylation-associated downregulation of the RXRG might play a crucial role in the development of NSCLC." (PMID 35631448, 2022).
schizophrenia (3 papers, 2015 to 2021). A major psychotic disorder characterized by abnormalities in the perception or expression of reality. "There is some previous association between RXRG and BD, as well as other disorders, such as schizophrenia." (PMID 26190982, 2015). "Our observation that loss of RXRγ impairs group 1 mGluR responses suggests that reduced group 1 mGluR activity may underlie, or contribute to schizophrenia-related impairments in RXRγ knockout mice." (PMID 33692389, 2021). "This study presents evidence for down-regulation of the nuclear receptors NR4A1, NR4A2, RXRB, and KLF4 mRNAs in the DLPFC in schizophrenia and evidence of reduced RARG and RXRG expression in females with schizophrenia." (PMID 27992436, 2016). "Our finding of decreased RARG and RXRG mRNA levels in females with schizophrenia may be related to changes found in estrogen and/or estrogen receptors (ER) signaling." (PMID 27992436, 2016).
endometritis (2 papers, 2021 to 2025). An acute or chronic, usually bacterial infectious process affecting the endometrium. "For example, RXRA and RXRG mRNA expression was significantly higher in the endometrial tissue of normal cows compared to repeat breeder cows and repeat breeder cows with subclinical endometritis." (PMID 40564281, 2025). "Similarly, expressions of IFNT, ISG15, CXCL10, PPARG, RXRG, SLC2A1, and SLC27A6 proteins were greater and MUC1 was lower in the endometrium of cows without endometritis compared with cows with endometritis (p < 0.05)." (PMID 33920430, 2021).
invasive breast carcinoma (2 papers, 2019 to 2025). A carcinoma that infiltrates the breast parenchyma. "In addition, RXRG has been proposed as an independent prognostic biomarker in estrogen receptor-positive invasive breast cancer." (PMID 40465540, 2025).
papillary thyroid carcinoma (2 papers, 2020 to 2025). "This study aimed to elucidate the functional role and underlying molecular mechanisms of retinoid X receptor γ (RXRG) in the pathogenesis of papillary thyroid carcinoma (PTC)." (PMID 40465540, 2025).
sarcopenia (2 papers, 2022 to 2024). Progressive decline in muscle mass due to aging which results in decreased functional capacity of muscles. "We found the AUC values of GPCPD1, MT1X, ARHGAP36, FAM171A1, ZNF415, and RXRG on the validation dataset were 0.928, 0.75, 0.978, 0.961, 0.811, and 0.906, indicating that the six biomarkers had high diagnostic accuracy for sarcopenia." (PMID 36147639, 2022). "Moreover, six hub genes with AUC exceeding 0.9, including ARHGAP36, FAM171A1, GPCPD1, MT1X, ZNF415, and RXRG, were confirmed as diagnostic biomarkers for sarcopenia." (PMID 36147639, 2022). "Finally, six hub genes with AUC exceeding 0.9, including GPCPD1, MT1X, ARHGAP36, FAM171A1, ZNF415, and RXRG, were defined as diagnostic biomarkers of sarcopenia." (PMID 36147639, 2022). "In this research, six genetic biomarkers closely associated with sarcopenia, including ARHGAP36, FAM171A1, GPCPD1, MT1X, ZNF415, and RXRG, were identified by WGNCA and LASSO analysis, which were used to future diagnose and screen for sarcopenia." (PMID 36147639, 2022). "Additionally, in patients with sarcopenia, MT1X and ARHGAP36 were upregulated, whereas FAM171A1, GPCPD1, ZNF415 and RXRG, were downregulated, demonstrating high diagnostic accuracy for sarcopenia and potential as predictive markers for screening." (PMID 38337720, 2024). "Compared to normal samples, the expression levels of both MT1X and ARHGAP36 were upregulated in sarcopenia samples, while GPCPD1, FAM171A1, ZNF415, and RXRG showed lower expression in sarcopenia samples." (PMID 36147639, 2022).
alopecia (1 paper, 2014). Hair loss usually from the scalp. "Animal studies have shown that VDR(−/−)/RXRG(−/−) mice exhibit features typical of vitamin D-dependent rickets type II, including growth retardation, impaired bone formation, hypocalcemia, and alopecia." (PMID 24641809, 2014).
Alzheimer disease (1 paper, 2020). A progressive, neurodegenerative disease characterized by loss of function and death of nerve cells in several areas of the brain leading to loss of cognitive function such as memory and language. "RXRγ was particularly found to be involved in the regulation of CNS myelination, a key process in multiple sclerosis with high relevance also in Alzheimer’s disease (AD)." (PMID 33187070, 2020).
bladder cancer (1 paper, 2022). "3.30.50.10.FF4220, a nuclear receptor family particularly likely to be free of side effects, contains proteins such as RXRA, RXRB and RXRG which show high expression in bladder cancer and are currently drug targets in other cancers (breast and prostate)." (PMID 35035776, 2022).
dementia (1 paper, 2018). Loss of intellectual abilities interfering with an individual's social and occupational functions. "Elevated levels of RXRα gene and protein expression have been found in individuals suffering from dementia, and knockout of RXRγ impairs the working memory in mice." (PMID 28815487, 2018).
demyelination (1 paper, 2019). "Of these, the 9-cis retinoic acid-responsive element RXRγ is known to be upregulated at the transition from NPCs to the OPC lineage, as well as at lesions in the lysolecithin-induced murine demyelination model." (PMID 31390799, 2019).
embryonal carcinoma (1 paper, 2009). A non-seminomatous malignant germ cell tumor characterized by the presence of large germ cells with abundant cytoplasm resembling epithelial cells, geographic necrosis, high mitotic activity, and pseudoglandular and pseudopapillary structures formation. "The hypothesis that in vitro and in vivo pathways are comparable is supported by significant up-regulation of RARα and RARβ mRNA, but rapid down-regulation of RARγ and RXRγ mRNA during RA-induced neuronal differentiation of mouse embryonal carcinoma cells." (PMID 19642999, 2009).
fragile X syndrome (1 paper, 2021). A genetic syndrome caused by mutations in the FMR1 gene which is responsible for the expression of the fragile X mental retardation 1 protein. "To explore the possibility that RXRγ-dependent reductions in group 1 mGluR signaling might affect fragile X syndrome-related phenotypes in a mouse model of fragile X, we crossed RXRγ knockout mice with Fmr1I304N mutant mice that carry a disease-linked point mutation in the gene encoding FMRP83." (PMID 33692389, 2021).
head and neck cancer (1 paper, 2025). A primary or metastatic malignant neoplasm affecting the head and neck. "Considerable increased mRNA expression of RXRG was found in head and neck cancer." (PMID 40465540, 2025).
Huntington disease (1 paper, 2015). Huntington disease (HD) is a rare neurodegenerative disorder of the central nervous system characterized by unwanted choreatic movements, behavioral and psychiatric disturbances and dementia. "G-4 genes included 6 genes: Btg3 associated nuclear protein (Banp), Ephx2, retinoid X receptor gamma (Rxrg), Ryr1, RNA-binding protein fox-1 homolog 1 (Rbfox1) and Zbtb16 categorized as ‘hereditary disorder (Huntington's disease)'." (PMID 26165378, 2015).
Hyperglycemia (1 paper, 2021). An increased concentration of glucose in the blood. "Besides the effects that hyperglycemia could have in CLZ-treated patients with refractory psychosis, we also identified relevant gene enrichment in the thyroid hormone signaling pathway, including the RXRA/RXRG genes." (PMID 33557049, 2021).
lymph node metastasis (1 paper, 2025). "Elevated RXRG expression correlated with aggressive clinicopathological features, including lymph node metastasis (P = 0.041), advanced tumor stage (P = 0.035), BRAFV600E mutation (P < 0.001), and increase in tumor size (P = 0.011)." (PMID 40465540, 2025).
memory impairment (1 paper, 2016). "These age-related memory impairments were associated with a hippocampal hypoexpression of RARα, RXRβ, and RXRγ mRNAs in middle-aged control animals." (PMID 27242514, 2016).
mental disorder (1 paper, 2015). A disease that has its basis in the disruption of mental process. "The GeneFriends analysis suggests that MCTP1 and RXRG coexpress with mental disorder related genes." (PMID 26190982, 2015). "However, MCTP1 and RXRG have 13 commonly coexpressed genes, which are significantly enriched for relevant disease annotations (e.g., “Brain diseases” and “Mental disorders”) and several relevant GO annotations (e.g., “Synaptic transmission”)." (PMID 26190982, 2015). "The large number of commonly coexpressed genes between RXRG and TNR, and the enrichment of these genes in mental disorder related annotations, strongly suggests that they are part of the same mental disorder related network." (PMID 26190982, 2015). "A systems genetics approach suggests that TNR, RXRG, and MCTP1 coexpress with several other genes related to mental disorders in the striatum, providing a potential mechanism of action." (PMID 26190982, 2015). "This suggests that although genes related to, for example, mental disorders are enriched in the overlap between TNR and RXRG, and in the overlap between MCTP1 and RXRG, they are not the same genes, i.e., both sets of genes are independently related to mental disorders." (PMID 26190982, 2015).
metastatic cancer (1 paper, 2020). A carcinoma which has spread from the original site of growth to another anatomic site. "Associations werefound with metastatic cancer (12/6; gains/losses), localized high (1/4;gain/losses) and low risk (1 loss; RXRG), prostateintraepithelial neoplasia (PIN) (2/1; gains/loss), and with theintermediate risk prostate cancer (6 losses)." (PMID 32159609, 2020).
multiple sclerosis (1 paper, 2019). A progressive autoimmune disorder affecting the central nervous system resulting in demyelination. "Interestingly, an agonist of RXRG, bexarotene, has been the focus of numerous recent studies in which it has been used to treat disease in mouse models of AD, Parkinson’s, ALS, multiple sclerosis and stroke." (PMID 30705335, 2019).
ovarian adenocarcinoma (1 paper, 2021). An adenocarcinoma that arises from the ovary. "Earlier in an ovarian adenocarcinoma progression model, activation of RXRG by retinoid treatment sensitized the cells to apoptosis." (PMID 34728699, 2021).
pemphigus (1 paper, 2021). Pemphigus is a group of rare autoimmune diseases that cause blistering of the skin and mucous membranes (mouth, nose, throat, eyes, and genitals).This conditioncan occur at any age, but often strikes people in middle or older age. "Several other skin homeostatic genes, including WIF1, EDA, RXRG, and TGFB2, were significantly decreased in pemphigus cases." (PMID 34660634, 2021).
pituitary tumours (1 paper, 2020). "Though only 20 high confidence variants were available for the signature analysis, this is not uncommon in pituitary tumours and the signature found raises the possibility of cooperation between the germline AHR and RXRG variants and somatic driver mutations." (PMID 31996203, 2020).
thyroid (1 paper, 2025). "Our data indicated that RXRG regulates tumor immune infiltration and promotes thyroid tumorigenesis by enhancing cell proliferation, colony formation, metastasis, and suppressing cell apoptosis." (PMID 40465540, 2025). "In addition to promoting cell metastasis through the induction of EMT, RXRG facilitated thyroid tumorigenesis by enhancing cell proliferation, colony formation, and resistance to cell apoptosis." (PMID 40465540, 2025). "Given that RXRG is frequently overexpressed in PTCs, this gene may play an oncogenic role in thyroid tumorigenesis." (PMID 40465540, 2025).
triple-negative breast carcinoma (1 paper, 2019). An invasive breast carcinoma which is negative for expression of estrogen receptor (ER), progesterone receptor (PR), and human epidermal growth factor receptor 2 (HER2). "In this study, ER-positive breast cancer showed the highest expression of RXRG compared to HER2+ and triple-negative breast cancer." (PMID 31558802, 2019). "High RXRG expression was primarily observed in luminal A tumours (136/214, 63.6%), while it was less expressed in HER2+ and triple-negative breast cancer." (PMID 31558802, 2019).
tumor (18 papers, 2010 to 2025). "This immunomodulatory activity, combined with RXRG’s direct oncogenic effects on tumor cells, likely contributes to its strong association with aggressive clinical features in PTC." (PMID 40465540, 2025). "Although this study primarily utilized THP-1-derived macrophages, the observed upregulation in RARγ and RXRγ during M2 polarization suggests that this regulatory mechanism may be conserved in primary human macrophages and tumor-associated macrophages in vivo." (PMID 40807274, 2025). "Favourable cases, we noted, are marked by THRA-mediated metabolic regulation, RXRG-driven tumour suppression, GCGR-maintained metabolic homeostasis, and FAAH-mediated resolution of inflammation." (PMID 41007296, 2025). "Our study identifies RXRG as a novel oncogenic driver in PTC that promotes tumor progression through EMT regulation and immune microenvironment modulation." (PMID 40465540, 2025). "Bioinformatics analysis was performed to explore the correlation between RXRG expression and tumor immune microenvironment." (PMID 40465540, 2025). "Retinoid X receptor gamma (RXRg) is a nuclear receptor for retinoids that is reported to play a role in the growth and differentiation of normal and tumor cells." (PMID 41439026, 2025). "The expression of RXRG in the PTC tumor samples was significantly overexpressed compared with that in the matched normal tissues in the validated cohort (T: n = 0.88 ± 0.70: 0.05 ± 0.047, P < 0.001)." (PMID 40465540, 2025). "The mRNA expression of genes of RXRγ, RARα, and RXRα was shown to be considerably lower in tumor specimens, revealing that deregulation of these genes follows the aberrant transformation of lung tissue cells." (PMID 35631448, 2022). "The authors found that the mRNA levels of the nuclear receptor genes RXRγ, RARα, RXRα were significantly decreased in 80%, 65%, and 57% of tumor specimens, respectively, even at early stages." (PMID 32012980, 2020). "The findings showed that RARα, RARβ, RARγ, and RXRγ were present in significantly lower levels in the tumor tissues." (PMID 32012980, 2020). "There was a significant positive linear correlation between RXRG and ER expression in the whole cohort and in ER-positive tumours (r = 0.30, p < 0.0001 and r = 0.20, p = 0.016, respectively)." (PMID 31558802, 2019). "RXRG has been demonstrated to modulate cellular differentiation and apoptosis in different tumour types." (PMID 31558802, 2019). "In ER-negative tumours, only MED7 (p < 0.00001), BEX1 (p = 0.032) and N-cadherin (p = 0.034) showed significant association with RXRG." (PMID 31558802, 2019). "Topotecan alone or the combined drug regimen of topotecan and melphalan effectively targeted proliferative tumor cones (RXRγ+ Ki67+) in organoids after 24-h drug exposure, blocking mitotic entry." (PMID 30353124, 2018). "Co-expression of RXRγ and Ki67 identified proliferative tumor cone cells and differentiated from RXRγ+ Ki67− resting tumor cones." (PMID 30353124, 2018). "Furthermore, RXRG expression considerably influenced tumor immune infiltration patterns, particularly affecting eosinophils, NK cells, and B cells." (PMID 40465540, 2025). "Univariate logistic regression analysis showed that the significant variables for LNM were age (OR 0.618, 95% CI: 0.422–0.904, P = 0.013), histological type (OR 0.41, 95% CI: 0.263–0.640, P < 0.001), tumor stage, and RXRG expression (OR 1.486, 95% CI: 1.017–2.173, P = 0.041)." (PMID 40465540, 2025). "Precancerous clusters showed enrichment in tumor progression-related regulons, including transcription factors (TFs) linked to tumor proliferation and cell cycle progression (STAT1, BCL6, ETV5) and potential tumor suppressors (ELF5, LTF, RXRG, CEBPD), as well as EMT-related regulons." (PMID 39872221, 2025). "Bioinformatics approaches were employed to investigate RXRG’s role in tumor immune infiltration." (PMID 40465540, 2025).